CCND1 (cyclin D1)
Diseases named in the same sentence as CCND1 in open-access papers (continued):
Sharing a sentence is not in itself a finding about the gene and the disease.
parathyroid tumors (13 papers, 2007 to 2025). "The overexpression of cyclin D1 in parathyroid neoplasms can be caused by pericentric inversion of chromosome 11p that results in CCND1 gene control by parathyroid hormone gene promoter." (PMID 35805976, 2022). "This miRNA is predicted to target and inhibit the CCDN1 gene, encoding the cyclin D1, a positive regulator of cell cycle and cell growth that has been found to be frequently over-expressed in parathyroid tumors." (PMID 34681865, 2021). "CCND1, encoding cyclin D1, was first identified as an oncogene in parathyroid tumors, and overexpression of this gene was found in 20-40% of PA samples." (PMID 34054720, 2021). "This is also in accordance with the fact that cyclin D1 stain lacks the ability to distinguish between benign vs. malignant parathyroid tumours." (PMID 35805976, 2022). "Cyclin D1 (CCND1) was originally identified as an oncogene in parathyroid tumors and is upregulated in lymphoid malignancies, including MM." (PMID 33494394, 2021). "Molecular alterations associated with parathyroid tumors include genomic aberrations in cell division cycle 7 (CDC7), cyclin D1 (CCND1), cyclin-dependent kinase inhibitor (CDKI), and multiple endocrine neoplasia type 1 (MEN1)." (PMID 33778063, 2021). "The over-expression of cyclin D1 protein is a common event in sporadic parathyroid tumors (20–40% of benign PAs and about 90% of malignant PCs)." (PMID 34681865, 2021). "As for other types of human cancers, over-expression of cyclin D1 in parathyroid tumor cells presumably derives from gene copy number alterations or chromosomal rearrangements and trans-acting altered regulation of gene expression, rather than activating mutations of the CCDN1 gene." (PMID 35282432, 2022). "A direct pathogenic role of cyclin D1 in parathyroid tumorigenesis has been demonstrated in transgenic mouse models containing a chromosomal rearrangement of the human CCND1 locus, mimicking the one found in two human parathyroid tumors, and over-expressing cyclin D1." (PMID 35282432, 2022). "Parathyroid tumours often demonstrate over-expression of cyclin D1, thus making the p16ink4A gene an interesting candidate for promoter methylation assays since p16ink4A inactivation might produce parallel oncogenic effects analogous to cyclin D1 up-regulation." (PMID 20208994, 2010). "Maintained activity of endogenous β-catenin was found to be necessary for the expression of MYC and cyclin D1 (CCND1), as well as growth and survival of a unique human parathyroid tumor cell line." (PMID 18044981, 2007).
psoriasis (12 papers, 2009 to 2025). An autoimmune condition characterized by red, well-delineated plaques with silvery scales that are usually on the extensor surfaces and scalp. "Our findings demonstrated that compared to treatment with deucravacitinib alone, Deu@PEPS is more effective in ameliorating the induction of multiple cytokines and important molecular features associated with psoriasis by STAT3-Krt17-Cyclin D1 pathway." (PMID 38799436, 2024). "In particular, cyclin D1 is overexpressed in keratinocytes and is associated with epithelial hyperproliferation in psoriasis." (PMID 23690852, 2013). "Measuring the Ki-67 level in comparison with cyclin D1 can also be helpful for the diagnosis of psoriasis." (PMID 39595528, 2024). "The alcohol component, ethanol, exacerbates the pathology of psoriasis by inducing keratinocyte proliferation through the activation of keratinocyte cyclin D1 and keratinocyte growth factor, which can lead to epidermal thickening in psoriasis." (PMID 34069063, 2021). "The expression of claudin, cyclin B1, cyclin D1, filaggrin, phospho-histone H2AX, kallikrein 7, Ki67, loricrin, NFAT5, and periplakin was assessed on punch biopsies obtained from eight psoriasis and six atopic eczema patients." (PMID 40559228, 2025). "Consistently, RT‒qPCR results showed that K17 KO also downregulated the mRNA levels of the proliferation markers K17, K16, PCNA, Cyclin D1 and key enzymes (GLUT1, PFKM, LDHA, HK2, PKM2, ENO1 and PGK1) in the IMQ-induced psoriasis-like model." (PMID 37497003, 2023). "Similarly, cyclin D1, CDK2, and CDK4 expression is increased in psoriatic lesions of psoriasis patients." (PMID 34639115, 2021). "Whereas cyclin D1 was negative or expressed in a low percentage of nuclei in psoriasis before therapy." (PMID 27473420, 2016). "Furthermore, vitamin D, a drug used in the treatment of psoriasis, downregulates EGFR and cyclin-D1." (PMID 19551138, 2009). "Similarly, western blot results revealed that the psoriasis model phenotype in vitro, including Akt and p65 pathways, were also activated after 12 h M5 treatment, along with FGF12 and cell proliferation factor Cyclin D1." (PMID 39234815, 2024). "Moreover, Ki67 expression and the mRNA levels of proliferation markers K17, K16, PCNA, Cyclin D1 and key enzymes (GLUT1, PFKM, LDHA, HK2, PKM2, ENO1 and PGK1) were also decreased in epidermal KCs of the IMQ-induced psoriasis-like model with local application of BI-D1870." (PMID 37497003, 2023).
rectal cancer (12 papers, 2009 to 2024). A primary or metastatic malignant neoplasm that affects the rectum. "The associations of PDE4 and Epac1 with AKAP95, Cx43, cyclin E1, and cyclin D1 in 44 rectal carcinoma samples were assessed." (PMID 30809467, 2019). "Studies reported that LINC00461 played an oncogenic role in CRC cells through the NFIB signaling pathway, and mediated cisplatin resistance of rectal cancer by targeting the miR-593-5p/CCND1 axis, showing that LINC00461 may be a prognostic biomarker for CRC." (PMID 33959151, 2021). "We previously assessed rectal carcinoma tissues and found higher positive rates of AKAP95, cyclin E1, and cyclin D1 compared with paracarcinoma tissues." (PMID 30809467, 2019).
hairy cell leukemia (11 papers, 2010 to 2025). Hairy cell leukemia (HCL) is a rare type of leukemia in which abnormal B-lymphocytes are present in the bone marrow, spleen and peripheral blood. "Except for cyclin D1 and BRAF, the immunophenotype was similar to that of hairy cell leukaemia." (PMID 40282427, 2025). "Hairy cell leukemia (HCL) may show positive for cyclin D1 and initially be misdiagnosed as MCL." (PMID 34442137, 2021). "In order to exclude lymph node involvement by hairy cell leukemia (HCL), all BRAF mutant NMZL were carefully reevaluted and stained for CD103 and Annexin A1 and turned out to be negative; in addition, all of them were negative for cyclin D1." (PMID 29556019, 2018).
malignant glioma (11 papers, 2011 to 2025). A grade III or grade IV glioma arising from the central nervous system. "CCND1 is a gene encoding the protein cyclin D1, which is overexpressed in malignant gliomas and positively associated with malignancy grade and poor prognosis." (PMID 39940838, 2025). "We then experimentally tested the regulatory role of cyclin D1 in the differentiation of human malignant glioma cells (U87-MG cells) by silencing CCND1, which encodes cyclin D1 protein, and pharmacologically downregulating or inhibiting cyclin D1." (PMID 27515956, 2016). "Overexpression of Cyclin D1 induces TMZ resistance by upregulating P-gp in human malignant glioma cells." (PMID 37830634, 2023). "CCND1 belongs to the Cyclin D family of cell cycle regulators, which are known to be up-regulated and amplified in malignant glioma." (PMID 30059495, 2018). "We next confirmed the expression level of Cyclin D1 protein in the adjacent normal brain tissues of malignant glioma from 32- to 86-year-old patients." (PMID 29033786, 2017). "Cyclin D1 protein is frequently overexpressed in malignant gliomas." (PMID 35223330, 2022).
mammary adenocarcinoma (11 papers, 2004 to 2024). "Cyclin D1 over-expression in mice leads to mammary adenocarcinoma associated with activated estrogen signaling pathways." (PMID 24575359, 2012). "In breast adenocarcinoma, cytoplasmic-membranous Ccnd1 protein expression was evaluated in 50 samples displaying different types of invasion (collective, glandular, indian-file)." (PMID 27105504, 2016). "Sustained expression of cyclin D1KE induced mammary adenocarcinoma with similar kinetics to that of the wild-type cyclin D1." (PMID 25940700, 2015). "Immunohistochemistry was used to compare relative expression levels of the hormone receptors ERα and PgR, cyclin D1, Ki67 and ErbB2 in the mammary adenocarcinomas that developed in the different genotypes across treatment groups." (PMID 24575359, 2012). "Yet mammary-directed overexpression of CCND1, an upstream regulator of pRbf, leads to mammary adenocarcinoma." (PMID 14966529, 2004). "Likewise, overexpression of cyclin D1 oncogene in cyclin D1 transgenic mice resulted in abnormal cell proliferation including mammary adenocarcinomas in females and a testicular sarcoma in males." (PMID 38500604, 2024). "Hormone receptor, cyclin D1, Ki67 and ErbB2 expression were detected in all the mammary adenocarcinomas without any significant differences between genotypes or treatment groups." (PMID 24575359, 2012).
ovarian tumors (11 papers, 1997 to 2025). "In a further study of 50 ovarian tumours, cyclin D1 overexpression was observed in 70% of tumours and linked with poor survival." (PMID 38612869, 2024). "In another immunohistochemical study of 134 ovarian tumours, cyclin D1 overexpression was associated with poor survival outcomes." (PMID 38612869, 2024). "In a previous study of 81 ovarian tumours, cyclin D1 overexpression was observed in 89% of cases [nucleus and cytoplasm co-expression in 30% and localisation exclusively in the cytoplasm in 59%]." (PMID 38612869, 2024). "There was a statistically significant higher gene expression of CCND1 in the ovarian tumours compared to the normal tissues." (PMID 38612869, 2024). "As a downstream target of active Akt, the expression of Cyclin D1 decreased in PTX-treated wt MCF-7 cells in relation to taxol reduced Cyclin D1 expression in ovarian tumors." (PMID 33019717, 2020). "Cyclin D1 was found to be overexpressed in 19% of ovarian tumors in one study, which was correlated with poor prognosis." (PMID 29644000, 2018). "Cyclin dependent kinase 1 (Ccnd1) was downregulated in response to E2 and altered in 8 % of ovarian tumors." (PMID 26879975, 2016). "Co-amplified genes were also prominent in the high-risk ovarian tumors including case OC-04 with high level CCNE1 amplification and co-amplification of CCND1, CCND3, MYC and ETV6 genes." (PMID 23289505, 2013). "Cyclin D1 was overexpressed in 18% of serous epithelial ovarian cancer and associated with a more aggressive tumor phenotype and poor prognosis, whereas CDK2 was shown to be amplified in a relatively small proportion (6.4%) of ovarian tumors." (PMID 32862831, 2020).
rhabdomyosarcoma (11 papers, 2013 to 2025). A rare aggressive malignant mesenchymal neoplasm arising from skeletal muscle. "Guo44 detected rhabdomyosarcoma cells treated with matrine at different concentrations by MTT, flow cytometry, and RT-PCR and found that matrine significantly inhibits the proliferation of rhabdomyosarcoma cells by reducing the expression of CCND1 mRNA and blocking the cell cycle of the G0/G1 phase." (PMID 32728182, 2020). "Similar effects have been reported for SAHA, which downregulates cyclin D1 and upregulates CDKN1A and CDKN1B in rhabdomyosarcoma models, indicating that HDACi broadly regulate cell cycle-associated genes." (PMID 40671124, 2025). "Downstream targeted genes of STAT3 such as CYCLIN D1, SURVIVIN, and BCL-XL in RH30, RD, and RH28 rhabdomyosarcoma cell lines were down-regulated when treated with Bazedoxifene." (PMID 28672024, 2017).
benign prostatic hyperplasia (10 papers, 2007 to 2025). A non-cancerous nodular enlargement of the prostate gland. "Assessment of immunohistochemical staining intensity through digital image analysis, corroborated by statistical testing, confirmed lower immunoreactivity of β-catenin, Fzd8, Wnt5a and cyclin D1 in prostate adenocarcinoma compared to benign prostatic hyperplasia." (PMID 41465498, 2025). "Our study results, indicating lower expression of β-catenin, Fzd8, Wnt5a and cyclin D1, may suggest attenuated activity of the Wnt/β-catenin pathway in prostate adenocarcinoma compared to benign prostatic hyperplasia." (PMID 41465498, 2025). "The observed effects of CB1 antagonists AM6545 or AM4113 against MetS-induced prostate hyperplasia might be attributed to their antiproliferative properties, as shown by the suppression of cyclin D1 expression." (PMID 37212036, 2023). "Specifically, mast cells have been suggested to induce benign prostatic hyperplasia epithelial cell proliferation via cyclin D1 pathway that involves transcription factors such as Janus family tyrosine kinase (JAK)-signal transducer and activator of transcription (STAT)." (PMID 36059933, 2022).
chronic myeloid leukemia (10 papers, 2015 to 2025). "For instance, miR-342-5p reduces cancer cell proliferation by targeting a cell cycle regulator Cyclin D1 (encoded by the CCND1 gene), and is reported to be downregulated in chronic myeloid leukemia patients." (PMID 36672402, 2023). "Moreover, an ethanol extract of a traditional Chinese medicine, Eupolyphaga sinensis Walker induced G2/M arrest of a chronic myeloid leukemia cell line K562 accompanying through downregulation of cyclin D1, cyclin E1 and cdc25C." (PMID 34513690, 2021). "Treatment of chronic myelogenous leukemia (CML) cells K562 cells and imatinib-resistant K562R cells with CTD induces mitotic arrest, mediated by activation of the cyclin B1/Cdc2 complex and downregulation of cyclin D1." (PMID 41041648, 2025). "The EO from the leaves of Pinus roxburghii induced apoptosis along with inhibition of NF-κB and inhibited the expression of genes associated to cell survival (survivin, c-FLIP, Bcl-2, Bcl-xL, c-Myc, c-IAP2), proliferation (cyclin D1), and metastasis (MMP-9) in KBM-5 (chronic myeloid leukemia) cells." (PMID 30441836, 2018). "The significantly enriched pathways included chemokine signaling pathway (which involved CCL2), focal adhesion (which involved THBS1 and THBS2), TGF-beta signaling pathway (which involved THBS1, THBS2, SMAD5, and SMAD6) and chronic myeloid leukemia (which involved TGFBR2 and CCND1)." (PMID 27716259, 2016).
gastric adenocarcinoma (10 papers, 2005 to 2025). "In gastric adenocarcinoma, highly expressed HOXD4 is associated with positive lymph node metastasis and enhanced proliferation of gastric adenocarcinoma by increasing c-Myc and cyclin D1." (PMID 37827698, 2023). "Consistent with our current findings, we have previously reported that gastrin enhanced cyclin D1 protein and cyclin D1 promoter activity in the human gastric adenocarcinoma cell line AGS-B." (PMID 15798764, 2005). "For example, unlike AGS-B cells, in AGS-E cells, a related human gastric adenocarcinoma cell line overexpressing the gastrin receptor, G-17 induction of cyclin D1 transcription was mediated through both β-catenin and CREB pathways." (PMID 15798764, 2005). "Interestingly, CDCA2 not only enhances the proliferation of CRC cells by activating the AKT/CCND1 pathway but also reduces the radiosensitivity of gastric adenocarcinoma by activating the PI3K/AKT pathway." (PMID 40565588, 2025). "A similar effect of pantoprazole on cyclin D1 was reported for gastric adenocarcinoma." (PMID 32164284, 2020). "Cyclin D1 is overexpression in MNNG-induced rat gastric adenocarcinomas." (PMID 31340453, 2019). "Of these, 8 regions contained previously characterized amplified oncogenes: GATA4, CCND1, CDK6, MDM2, EGFR, MCL1, ERBB3 and MYB; this is the first report of significant and nearly isolated MYB amplification in gastric adenocarcinoma." (PMID 28426752, 2017). "However, to our knowledge, dysregulation of cyclin D1, RANKL, LSD1, Autotaxin, Calpain2, XIAP, IGF-Irβ, ASC-R and BID in AFP producing gastric adenocarcinoma has not been reported before." (PMID 27057629, 2016).
invasive carcinoma (10 papers, 2008 to 2024). A carcinoma that is not confined to the epithelium, and has spread to the surrounding stroma. "This activates cyclin D1, leading to greater proliferative activity and higher frequency of mutations, thus rendering the cell more susceptible to permanent genetic changes, that in turn may give rise to genomic instability and invasive carcinoma." (PMID 21547265, 2011). "Claudin-1 expression was reduced in 74% of patients belonging to the>40 years age group (as seen in cyclin D1 expression) and those with grade 2 and grade 3 invasive carcinoma, measuring more than 2 cm in size." (PMID 40034931, 2024). "Cyclin D1 nuclear expression was observed in 38% of the cases, majorly belonging to > 40 years age group and having grade 2 invasive carcinoma (22%) ranging between 2 and 5 cm (pT2) in size (13 out of 44 patients)." (PMID 40034931, 2024). "We measured the HER2, C-MYC, CCND1 and FGFR1 amplification status in pure DCIS, DCIS associated with invasive carcinomas, and invasive carcinomas." (PMID 22863309, 2012). "In order to simulate the stiffness range of the in vivo normal tissue and invasive carcinoma, that was reported to be from 3 to 13 kPa, MDAPSFs with different stiffnesses were produced using 2.25, 4.5 and 9 % (w/v) of PEGDa and the cyclin D1 expression was assessed." (PMID 38046276, 2023). "In this study, we compared the gene amplification frequencies of HER2, C-MYC, CCND1 and FGFR1 in a relatively large series of pure DCIS, DCIS associated with invasive carcinoma, and invasive carcinomas, to investigate the role of gene amplification in the progression of DCIS to invasive carcinomas." (PMID 22863309, 2012). "In summary, we have studied the amplification frequencies of HER2, C-MYC, CCND1 and FGFR1 in a large series of pure DCIS, DCIS associated with invasive carcinoma, and invasive carcinomas, to investigate the role of gene amplification in the progression of DCIS to invasive carcinoma." (PMID 22863309, 2012). "Mu and colleagues (2011) also identified CCND1 amplification in invasive carcinoma which was absent in matched adjacent DCIS in three of 16 (18.8 %) cases." (PMID 26078038, 2015). "CCND1 amplification was correlated with HER2 and FGFR1 amplification in invasive carcinoma, but not in the pure DCIS." (PMID 22863309, 2012). "However, we detected amplification in the DCIS components but not in the invasive carcinoma components in a few cases for HER2 (n = 2), C-MYC (n = 2) and CCND1 (n = 3)." (PMID 22863309, 2012).